PDGFRA (platelet derived growth factor receptor alpha)
Diseases named in the same sentence as PDGFRA in open-access papers (continued):
Sharing a sentence is not in itself a finding about the gene and the disease.
gastrointestinal stromal tumor (continued). "Activating mutations in KIT are responsible for most of the gastro-intestinal stromal tumors (GIST) and many of the current therapies that target KIT and PDGFRA proteins result in the onset of resistance." (PMID 30682828, 2019). "Gastrointestinal stromal tumors (GIST) carrying the D842V activating mutation in the platelet-derived growth factor receptor alpha (PDGFRA) gene are a very rare subgroup of GIST (about 10%) known to be resistant to conventional tyrosine kinase inhibitors (TKIs) and to show an indolent behavior." (PMID 29510530, 2018). "Mutations in PDGFR family genes, particularly PDGFRα and c-KIT, are most frequently found in gastrointestinal stromal tumors (GISTs)." (PMID 30404198, 2018). "KIT, PDGFRA, NF1 and SDH mutations are alternate initiating events, fostering hyperplasia in gastrointestinal stromal tumours (GISTs), and additional genetic alterations are required for progression to malignancy." (PMID 28270683, 2017). "Gastrointestinal stromal tumor (GIST) is the most common sarcoma, often resulting from a KIT or platelet-derived growth factor receptor alpha (PDGFRA) mutation." (PMID 29371979, 2017). "Constitutive activating mutations inKIT and platelet-derived growth factor receptor α (PDGFRα) are heavily involved in the pathobiology of gastrointestinal stromal tumors (GISTs)." (PMID 28928967, 2017). "About 10–15% of adult, and most pediatric, gastrointestinal stromal tumors (GIST) lack mutations in KIT, PDGFRA, SDHx, or RAS pathway components (KRAS, BRAF, NF1)." (PMID 27974047, 2016). "Approximately 10–15 % of gastrointestinal stromal tumors (GISTs) lack gain of function mutations in the KIT and platelet-derived growth factor receptor alpha (PDGFRA) genes." (PMID 26555092, 2015). "Gastrointestinal stromal tumors (GISTs) are mesenchymal tumors of the gastrointestinal tract, which are characterized in the majority of cases by activating mutations in KIT and platelet-derived growth factor receptor alpha (PDGFRA)." (PMID 24802226, 2014). "Minimal overlapping regions in wild-type/PDGFRA-mutant gastrointestinal stromal tumors and the corresponding genes." (PMID 24124608, 2013). "A reciprocal relationship between IGF-IR and PDGFRα/c-kit expression has also been observed in gastrointestinal stromal tumors." (PMID 22070644, 2011). "Molecular analyses of the c-kit and PDGFRα genes have contributed greatly to our understanding of the development of gastrointestinal stromal tumors (GISTs), but little is known about their malignant potential." (PMID 18651966, 2008). "Gastrointestinal stromal tumors (GISTs) are the most common mesenchymal neoplasms of the gastrointestinal tract and originate from the interstitial cells of Cajal, with most driven by activating mutations in KIT or PDGFRA." (PMID 41517566, 2026). "This cohort study patients with platelet-derived growth factor receptor α (PDGFRA)-mutant GIST who underwent F 18–labeled positron emission tomography ([18F]FDG-PET) assess the degree of [18F]FDG uptake of PDGFRA-mutant gastrointestinal stromal tumors, with a focus on the D842V-mutant subgroup." (PMID 39853981, 2025). "Gastrointestinal stromal tumors (GIST) are the most common mesenchymal tumors of the gastrointestinal tract, primarily driven by mutations in the KIT (∼80%)and Platelet-Derived Growth Factor Receptor Alpha (PDGFRA) (∼5%–10%) genes." (PMID 40170718, 2025). "Gastrointestinal stromal tumors (GISTs) are the most common mesenchymal tumors of the gastrointestinal tract, primarily driven by activating mutations in KIT (CD117) and platelet-derived growth factor receptor alpha (PDGFRA)." (PMID 40733131, 2025). "Interestingly, PDGFRA proteins are reliable biomarkers of gastrointestinal stromal tumors (GISTs) that respond to overall survival improvement with imatinib therapy." (PMID 40725249, 2025).
gastrointestinal stromal tumor (continued). "For example, TCs hyperplasia has been reported in inflammatory fibroid polyp neoplasia and platelet-derived growth factor receptor α (PDGFRα) mutant gastrointestinal stromal tumors, and the number of TCs was found to decrease in basal cell carcinoma and squamous cell carcinoma." (PMID 39605983, 2024). "Also interesting is the expression of CD117 and PDGFRA, which creates difficulties for the differential diagnosis with gastrointestinal stromal tumors (GISTs) in some atypical locations." (PMID 37108696, 2023). "Primary double KIT/PDGFRA mutations are very rare in gastrointestinal stromal tumours (GISTs) but have not been comprehensively studied to date." (PMID 36890498, 2023). "DOG1 is expressed in ~99% of gastrointestinal stromal tumors (GISTs) derived from Cajal cells regardless of conventional KIT (CD117) or platelet derived growth factor receptor alpha (PDGFRA) mutation status." (PMID 36776873, 2023). "Rare gastrointestinal stromal tumors (GISTs) are caused by mutations in the KIT and PDGFRA genes." (PMID 38004483, 2023). "Gastrointestinal stromal tumors lacking the KIT/PDGFRA mutations, however, represent distinct clinico-pathological entities with diverse molecular mechanisms of oncogenesis." (PMID 36900287, 2023). "Gastrointestinal stromal tumors (GIST) are rare sarcoma subtypes likely arising from the interstitial cells of Cajal after mutations to the c-kit gene affecting the tyrosine kinase receptor or the platelet-derived growth factor receptor alpha (PDGF-Rα)." (PMID 36428467, 2022). "Succinate dehydrogenase deficient (SDH-deficient) gastrointestinal stromal tumors (GISTs), as defined by the expression loss of the subunit B of the succinate dehydrogenase complex, account for approximately 20% to 40% of all KIT/PDGFRA wild-type (WT) GISTs and 5% of all GISTs." (PMID 33806389, 2021). "Gastrointestinal stromal tumors (GISTs) associated with SDH deficiency are negative for KIT/PDGFRA mutations and present with distinctive clinical features such as early onset (usually childhood or adolescence) and almost exclusively gastric location." (PMID 34012423, 2021). "The discovery of constitutive activating mutations in the proto-oncogene receptor tyrosine kinase (KIT) or platelet-derived growth factor receptor α (PDGFRA) oncogenes as molecular drivers of most gastrointestinal stromal tumors (GISTs) has radically changed our knowledge on their tumor biology." (PMID 33673554, 2021). "Gastrointestinal stromal tumors (GIST) are the most common mesenchymal tumors of the gastrointestinal tract and are characterized by activating mutations of the receptor tyrosine kinases KIT or PDGFRA." (PMID 25781619, 2015). "Additionally, the discovery and treatment of the targetable alterations in hot spot regions in the KIT or PDGFRA genes in gastrointestinal stromal tumors (GIST) has significantly improved overall survival of these patients." (PMID 26415226, 2015). "The best example of a successful RTK-inhibitor is imatinib that inhibits both c-KIT and platelet-derived growth factor receptor alpha (PDGFRα) and it is currently used for treating, amongst others, gastrointestinal stromal tumors (GISTs) and chronic myeloid leukemia (CML)." (PMID 25025175, 2014). "Unprecedented improvement in advanced gastrointestinal stromal tumors (GIST management has been achieved due to recent recognition of the important biological role of activating mutations in KIT and PDGFRA (platelet-derived growth factor receptor- alpha) genes." (PMID 22439647, 2012). "Gastrointestinal stromal tumors (GISTs) are the most frequent mesenchymal neoplasms of the gastrointestinal tract and are characterized by activating mutations of KIT or platelet-derived growth factor receptor alpha (PDGFRA)." (PMID 22662219, 2012).
gastrointestinal stromal tumor (continued). "The discovery of underlying molecular genetic abnormalities in gastrointestinal stromal tumors (GISTs) such as activating mutations in the tyrosine kinase genes, KIT and platelet derived growth factor receptor-alpha (PDGFRA), has led to remarkable clinical advances in treatment." (PMID 23036227, 2012). "ctDNA sequencing efficiently detects KIT/PDGFRA mutations and prognosticates outcomes in patients with TKI‐resistant gastrointestinal stromal tumor (GIST) treated with avapritinib." (PMID 40656546, 2025). "In cancers such as gastrointestinal stromal tumors (GIST) and gliomas, PDGFRA-driven fibrosis creates an immune-suppressive environment that limits immune cell infiltration and promotes tumor survival." (PMID 40817072, 2025). "Gastrointestinal stromal tumor (GIST), commonly occurring in the gastrointestinal tract, is a mesenchymal cell tumor usually driven by activating mutations in the receptor tyrosine kinase proto-oncogene, KIT, or the platelet-derived growth factor receptor α (PDGFRα)." (PMID 39834833, 2024). "NTRK fusions are mutually exclusive and are uncommonly identified in a subset of KIT/PDGFRA wild-type gastrointestinal stromal tumors (GIST)." (PMID 38200576, 2024). "Presently, gastrointestinal stromal tumors (GIST) are increasing rapidly worldwide, mostly due to mutations in KIT and PDGFRA genes." (PMID 35187038, 2022). "Chinese consensus guidelines for diagnosis and management of gastrointestinal stromal tumor recommend KIT/PDGFRA gene testing for CD117/DOG1-negative GIST patients, which acts as a supplement for immunohistochemical diagnosis." (PMID 35547262, 2022). "Wild-type KIT and PDGFRA gastrointestinal stromal tumors (GIST) are rare tumors with limited treatment options." (PMID 35388076, 2022). "Avapritinib, a potent inhibitor of KIT and platelet-derived growth factor receptor A (PDGFRA) tyrosine kinases, has demonstrated unprecedented clinical activity in PDGFRA D842V-mutant gastrointestinal stromal tumors (GIST)." (PMID 33740926, 2021). "Gastrointestinal stromal tumors (GIST) are the most common mesenchymal tumors of the digestive tract, and are mainly driven by activating mutations in KIT (also known as CD117) or platelet-derived growth factor A (PDGFRA), accounting for 0.1–3% of all gastrointestinal tumors." (PMID 34805171, 2021). "Gastrointestinal stromal tumours (GIST) are the most common mesenchymal tumours of the gastrointestinal tract, and the majority of adult onset GIST, so-called ‘tyrosine kinase mutant’ GIST (TK-mutant GIST), are driven by activating somatic mutations in the KIT or PDGFRA genes." (PMID 33443647, 2021). "A gastrointestinal stromal tumor (GIST), the most common sarcoma, is most often driven by oncogenic KIT or PDGFRA mutations." (PMID 33568624, 2021). "Other malignancies with dysregulated PDGFRA signaling, such as gastrointestinal stromal tumors (GIST), have received treatment with tyrosine kinase inhibitors (TKI)." (PMID 31480474, 2019). "With the gastrointestinal tract as the cause, gastrointestinal stromal tumor (GIST) is seen as the very widespread mesenchymal tumor, and most patients with GIST exhibit activation of the KIT and platelet-derived growth factor receptor (PDGFRA) mutations." (PMID 31032364, 2019). "Gastrointestinal stromal tumors (GISTs), the most common mesenchymal tumors of the gastrointestinal tract, result from constitutively activating mutations in two oncogenes from the receptor tyrosine kinase family, KIT or platelet-derived growth factor receptor-α (PDGFRA)." (PMID 28402935, 2017). "Recent advances in molecular biology have revolutionized the concept of KIT/PDGFRA wild type (WT) gastrointestinal stromal tumors (GIST) than the past." (PMID 28535771, 2017).
gastrointestinal stromal tumor (continued). "Gastrointestinal stromal tumors (GIST) that lack KIT or platelet-derived growth factor receptor alpha (PDGFRA) mutations, that are around 10–15% of all cases, have always been classified as KIT/PDGFRA wild type GIST, short-named WT GIST." (PMID 28535771, 2017). "Oncogenic mutations in KIT occur in 75-80% of gastrointestinal stromal tumors (GIST) and in 20-25% in PDGFRA." (PMID 29312620, 2017). "Several small studies indicated that the genotype of KIT or platelet-derived growth factor receptor-α (PDGFRA) contributes in part to the level of clinical effectiveness of sunitinib in gastrointestinal stromal tumor (GIST) patients." (PMID 26772734, 2016). "Gastrointestinal stromal tumors (GISTs) develop within the digestive tract and harbor functional mutations of KIT (v-kit Hardy-Zuckerman 4 feline sarcoma viral oncogene homolog) and PDGFRA (platelet-derived growth factor receptor-α) that primarily drive the tumor growth and progression." (PMID 26867653, 2016). "Gastrointestinal stromal tumors or “GIST” are mesenchymal neoplasms expressing KIT(CD117) tyrosine kinase and showing the presence of activating mutations in KIT or PDGFRα (platelet-derived growth factor alpha)." (PMID 23585972, 2013). "The discovery and the characterization of KIT/PDGFRA role in GISTs pathogenesis has led to a better identification of GIST among others gastrointestinal stromal tumors and to the development of targeted therapies in this disease." (PMID 23593401, 2013). "Neurofibromatosis type 1 (NF1)-associated gastrointestinal stromal tumor (GIST) is a distinct subtype of wild-type GIST driven by loss of neurofibromin function rather than KIT or PDGFRA mutations." (PMID 42176217, 2026). "Previously known as intestinal neurofibromatosis/neurofibromatosis 3b (INF/NF3b), this disease is now classified as a familial gastrointestinal stromal tumor (GIST) due to its genetic makeup, which was identified when GIST was the sole PDGFRA-mutant tumor found in the gastrointestinal tract." (PMID 38305808, 2024). "Gastrointestinal stromal tumors (GISTs) are the predominant mesenchymal tumors within the gastrointestinal tract, primarily driven bymutations in the c-KIT or PDGFRα genes." (PMID 39917203, 2024). "While secondary resistance to imatinib is rare, it typically involves one of two specific mutations: PDGFRA T674I, which has shown in vitro response to ponatinib, or PDGFRA D842V, for which avapritinib, approved for gastrointestinal stromal tumors (GIST), holds promise." (PMID 39037514, 2024). "Imatinib, a tyrosine kinase inhibitor (TKI) that targets ABL, BCR-ABL, PDGFRA, and c-KIT, is widely used in treating chronic myelogenous leukemia (CML) and gastrointestinal stromal tumors (GIST)." (PMID 39589949, 2024). "This study aims to evaluate whether CT based sarcopenia could differentiate KIT/PDGFRA wild-type gastrointestinal stromal tumor (wt-GIST) from the mutant-type GIST (mu-GIST), and to evaluate genetic features of GIST." (PMID 36828845, 2023). "Gastrointestinal stromal tumors (GISTs) are common ICC precursor sarcomas, which are considered to be a potential malignant mesenchymal tumor driven by specific KIT or PDGFRA signals in the gastrointestinal tract." (PMID 35646090, 2022). "KIT/PDGFRA wild type gastrointestinal stromal tumors (wtGIST) account for the remaining 15% of GIST and represent an unmet medical need: their prevalence and potential medical vulnerabilities are not completely defined, and effective therapeutic strategies are still lacking." (PMID 36142281, 2022).
gastrointestinal stromal tumor (continued). "PDGFRA and PDGFRB exert a central function in the initiation and progression of many tumors, including glioblastoma, gastrointestinal stromal tumor, skin squamous cell carcinoma, and oral squamous cell carcinoma." (PMID 36421685, 2022). "The alterations in PDGFRA are found explicitly in gastrointestinal stromal tumors (GIST)." (PMID 35621644, 2022). "SDH-deficient gastrointestinal stromal tumors (GIST) account for 20–40% of all KIT/PDGFRA-negative GIST." (PMID 35059314, 2021). "SDH-deficient gastrointestinal stromal tumors (GIST) account for 20–40% of all KIT/PDGFRA-negative GIST and are due to mutations in one of the four SDH-complex subunits, with SDHA mutations as the most frequent." (PMID 35059314, 2021). "Avapritinib also exerts activity against platelet-derived growth factor receptor alfa (PDGFRA) mutants, and was approved by the FDA in 2020 for the treatment of adults with unresectable or metastatic gastrointestinal stromal tumor (GIST) harboring PDGFRA exon 18 mutations." (PMID 33804174, 2021). "Conversely, other diseases characterized by hyperactivity of tyrosine kinases, such as PDGFRα in gastrointestinal stromal tumor (GIST) and hypereosinophilic syndrome or c-Kit in systemic mastocytosis, can benefit from imatinib and other inhibitors with wide selectivity spectrum." (PMID 29925402, 2018). "Gastrointestinal stromal tumors (GISTs) are the most common mesenchymal tumor in the gastrointestinal tract, the most common of which are KIT or PDGFRα (platelet-derived growth factor receptor alpha) activation mutations." (PMID 27845908, 2017). "Gastrointestinal stromal tumor (GIST), the most major mesenchymal neoplasm of the digestive tract, is characterized by KIT or platelet-derived growth factor receptor alpha (PDGFRA) activating mutations, which approximately account for 80% or 10% of GISTs respectively." (PMID 27506146, 2016). "Gastrointestinal stromal tumors (GIST) are among the most commonly diagnosed mesenchymal tumors and are typically characterized by gain of function mutations in receptor tyrosine kinases (RTKs) KIT or PDGFRA." (PMID 27167336, 2016). "Distinguishing a leiomyosarcoma from the most commonly encountered mesenchymal gastrointestinal tumor (i.e., the gastrointestinal stromal tumor, GIST, characterized by the presence of activating mutations in KIT or PDGFRA, and expression of CD 117 and/or CD34) is highly important." (PMID 27631424, 2016). "Gastrointestinal stromal tumors are characterized by genetic alterations of the activating tyrosine-kinase receptor, KIT (found in 80 % of tumors), and PDGFRA (found in approximately 10 % of tumors)." (PMID 26753123, 2015). "AMACR-specific fluorescence in situ hybridization and immunohistochemistry were both informative in tissue microarray sections of 350 independent primary gastrointestinal stromal tumors, including 213 cases with confirmed KIT /PDGFRA genotypes." (PMID 25473890, 2014). "The benefit that can be derived from accurate characterization of the biology of sarcomas is exemplified by treating gastrointestinal stromal tumors with molecules that inhibit c-KIT and PDGFRA." (PMID 24216705, 2013). "Sunitinib (Sutent®) is a multikinase inhibitor of VEGFR 1–3, RET and PDGFRα/β, currently approved for the treatment of RCC, imatinib-resistant gastrointestinal stromal tumors (GIST) and pancreatic neuroendocrine tumors (pNET)." (PMID 22072937, 2011). "PDGFs and their corresponding receptors, PDGFRα and PDGFRβ, exhibit expression in a diverse range of malignant tumors, such as non-small cell lung cancer (NSCLC), gastrointestinal stromal tumor (GIST), pancreatic cancer, breast cancer, ovarian carcinoma and hepatocellular carcinoma." (PMID 41334166, 2025).